LDHA (lactate dehydrogenase A)
Diseases named in the same sentence as LDHA in open-access papers (continued):
Sharing a sentence is not in itself a finding about the gene and the disease.
liver cancer (35 papers, 2017 to 2025). An epithelial or non-epithelial malignant neoplasm that arises from the liver. "LDHA is overexpressed in a variety of tumor cells, and the silencing of RNAi causes apoptosis to occur in liver cancer due to increased ROS production." (PMID 37892405, 2023). "In a model of MYC‐driven liver cancer, upregulation of lactate dehydrogenase A (LDHA) and LDHA‐dependent aerobic glycolysis was associated with the acquisition of a fully transformed phenotype." (PMID 36214609, 2022). "Wogonin inhibits gene expression of glycolytic associated factors like HK2 and LDHA in ovarian and liver cancer cells, hence limiting glycolysis and cell proliferation." (PMID 36339566, 2022). "Additionally, we analyzed the expression of ADAMTS5, CDCA8, and LDHA, the top three high-risk genes, in a liver cancer tissue array comprising 57 paired liver cancer tissues." (PMID 40647517, 2025). "We hope to further analyze the mechanism by which LDHA in T cells regulates the progression of cirrhosis and the occurrence of liver cancer." (PMID 38993839, 2024). "Based on data from two distinct databases (ICGC_LIRI and TCGA_LIHC), a comparative analysis of LDHA mRNA expression levels in liver cancer tissues across various stages was conducted." (PMID 38993839, 2024). "Under hypoxic conditions, enhanced glycolysis in liver cancer cells activates lactate dehydrogenase A (LDHA), leading to increased lactate production." (PMID 39610917, 2024). "The expression of LDHA was increased in liver cancer, and a large amount of energy wasrapidly generated through glycolysis to support cancer cell growth." (PMID 37663261, 2023). "In this study, we treated liver cancer cells with I3C, performed colony formation and cell migration, measured the expression of glycolysis-related proteins, and predicted and validated LDHA-targeting miRNA from the databases." (PMID 36297369, 2022). "The relationship between the expression levels of miR-34a and LDHA and liver cancer patient survival rate was examined using the Kaplan–Meier Plotter tool." (PMID 36297369, 2022). "Consistently, suppression of miR-3662 elevated the expression levels of GLUT1, HK2, PKM2, and LDHA in liver cancer cells." (PMID 29748591, 2018). "Our results showed that ectopic expression of miR-3662 decreased the levels of GLUT1, HK2, PKM2, and LDHA in liver cancer cells after treatment with the hypoxia mimetic CoCl2, while silencing miR-3662 increased their expression levels." (PMID 29748591, 2018). "Moreover, knockdown of BFSP1 significantly inhibited the expression of glycolysis-related proteins PKM2, GLUT1, PGK1, and LDHA in liver cancer cells, whereas overexpression of BFSP1 promoted the expression of the glycolysis-related proteins." (PMID 40097750, 2025). "LDHA catalyzes the final step of glycolysis, converting pyruvate to lactate, and is frequently overexpressed across diverse cancer types including breast, lung, prostate, pancreatic, brain and liver cancers." (PMID 41163796, 2025). "For people with hepatitis B, targeting LDHA or PDK could offer new strategies to reduce oxidative stress and thus the risk of liver cancer." (PMID 38655824, 2024). "Here, we report that machilin A (MA), which acts as a competitive inhibitor by blocking the nicotinamide adenine dinucleotide (NAD) binding site of LDHA, suppresses growth of cancer cells and lactate production in various cancer cell types, including colon, breast, lung, and liver cancers." (PMID 31324019, 2019). "Licorice roots extract induced apoptosis and cycle arrest of liver cancer cells, inhibited HK2, PKM2, and LDHA enzymes, and inhibited glycolysis by up-regulating multiple tumor suppressor genes miRNAs." (PMID 37663261, 2023).
liver cancer (continued). "Wogonin has been demonstrated to decrease the expression of HK2, LDHA, and GLUT1, hence reducing glycolysis and cell proliferation in ovarian and liver cancer cells." (PMID 36339566, 2022). "Further explorations show that an adenylate kinase, hCINAP, promotes FGFR1-catalyzed LDHA Y10 phosphorylation in CRC and an lncRNA, HULC, modulates the phosphorylation of LDHA Y10 through FGFR1, elevating aerobic glycolysis of liver cancer cells." (PMID 36407005, 2022). "The study demonstrated the expression of the glycolytic enzyme lactate dehydrogenase A (LDHA) regulates the expression of PI3K-Akt signaling results in the re-programing of bioenergetic mechanisms in breast and liver cancer progression." (PMID 34768921, 2021). "Western blotting results showed that Glut1, HK2, LDHA, and PDK1 expression increased and the CCK8 assay showed that knocking out Bclaf1 promoted the reduction by CK of hypoxic liver cancer cell viability." (PMID 33363466, 2020). "Under hypoxic conditions, NONO binds to mRNAs of glycolytic genes GLUT1, HK2, and LDHA, promoting their splicing maturation and increasing glycolysis levels in liver cancer cells." (PMID 38785569, 2024). "A study showed that curcumin could also down-regulate glycolytic-related factors HIF-1α, LDHA, MCT1 and MDR1, STAT3 gene expression in liver cancer cells, resulting in the elevation of micro-enviromental pH to combat lactate-induced drug resistance to doxorubicin." (PMID 36339566, 2022).
lung adenocarcinoma (35 papers, 2015 to 2026). A carcinoma that arises from the lung and is characterized by the presence of malignant glandular epithelial cells. "This study shows that LDHA is a risk factor for lung adenocarcinoma, which is consistent with literature reports." (PMID 41003841, 2025). "In conclusion, LDHA is positively associated with the progression and prognosis of lung adenocarcinoma." (PMID 38567154, 2024). "Other cancer types such as LUSC, OV, bladder urothelial carcinoma (BLCA), and lung adenocarcinoma (LUAD) also had a significant number of patients with LDHA CNV variants." (PMID 38198170, 2024). "The expression of LDHA in tumor tissues of lung adenocarcinoma increases with the advancement of the pTNM stage and lymphatic metastasis, suggesting that LDHA may be associated with abnormal immune function." (PMID 38567154, 2024). "In addition, according to GSEA analysis, high expression of LDHA in lung adenocarcinoma tissues was also positively correlated with hallmark gene sets of glycolysis and hypoxia, indicating the reliability of the results." (PMID 33902615, 2021). "In addition, LDHA can be used as a possible prognostic marker for lung adenocarcinoma survival, and the high expression of LDHA is associated with poor prognosis." (PMID 33912215, 2021). "Therefore, it can be concluded that the overexpression of LDHA may cause an increase in plasma oxalate in lung adenocarcinoma patients, and inhibition of LDHA may reduce oxalate production." (PMID 38567154, 2024). "Here, it is found that lactylation promotes the enzymatic activity of LDHA in lung adenocarcinoma (LUAD), which in turn enhances the overall level of cellular lactylation through a positive feedback loop." (PMID 41190808, 2026). "To investigate the clinical significance of LDHA lactylation, we detected lactylation of LDHA in paired tumor and adjacent normal tissues from four patients with lung adenocarcinoma using immunoprecipitation." (PMID 41190808, 2026). "In our study, we found the characteristic genes that affected lung adenocarcinoma through the propionate pathway included LDHA, KYNU, SLC2A1, CFTR, and MAOB." (PMID 41003841, 2025). "Studies have confirmed the overexpression of LDHA in renal cell carcinoma, oral squamous cell carcinoma, cervical cancer, lung adenocarcinoma, and cholangiocarcinoma." (PMID 39582531, 2024). "To further confirm the biological role of LDHA, we chose the human lung adenocarcinoma cell line NCI-H441 to conduct the experiment." (PMID 38709280, 2024). "In summary, our study highlights the pivotal role of LDHA in maintaining energy metabolism and chemotherapy sensitivity in lung adenocarcinoma." (PMID 39680520, 2024). "The results indicated a significantly higher expression of LDHA in lung adenocarcinoma tissue compared to normal lung tissue." (PMID 38567154, 2024). "On the other hand, knocking down the expression of LDHA in lung adenocarcinoma cells inhibits the proliferation, invasion, migration and colony formation." (PMID 31737570, 2019). "In highly glycolytic NSCLCs (accounting for >85% LCs), LDHA overexpression is the key event for the enhancement of aerobic glycolysis, which promotes tumour malignant behaviour, and invasive ability through the activation of epithelial–mesenchymal transition in lung adenocarcinoma." (PMID 36615660, 2022). "TCGA and GTEx database results showed significant differences in the expression of enzymes and transporters related to oxalate metabolism (LDHA, GRHPR, AGT, DAO, HAO2 and SLC26A1) in tumor tissues of lung adenocarcinoma patients." (PMID 38567154, 2024). "Lactate dehydrogenase A (LDHA) is an enzyme that plays a particularly important role in cancer cell metabolism and tumor growth, and is connected with poor prognosis in lung adenocarcinoma." (PMID 34323652, 2021).
lung adenocarcinoma (continued). "BUB1B knockdown could decrease the glycolysis-related genes, including solute carrier family 2 number 1, LDHA, pyruvate kinase M 2, and hexokinase 2, suggesting that BUB1B acts as an activator in glycolytic metabolism to promote lung adenocarcinoma." (PMID 38711083, 2024). "In this research, samples of lung adenocarcinoma were interrogated with TME-related genes, among which high expression of PLK1, LDHA, FURIN, FSCN1, and RAB27B was correlated with poor OS, while high expression of MS4A1 was correlated with longer OS compared with the MS4A1 low expression." (PMID 37604869, 2023). "In addition, our analysis of TCGA data on lung adenocarcinoma revealed that elevated expression of hypoxia-inducible factor 1A (HIF1A), lactate dehydrogenase A (LDHA), lactate dehydrogenase B (LDHB) and SLC16A1 is significantly correlated with poor prognosis." (PMID 34150616, 2021). "Not regulated in LCSC-like cells but regulated in the lung adenocarcinoma cell line LXF-289 were lactate dehydrogenase A (LDHA) and MYC mRNA expressions, as LDHA was significantly reduced and MYC significantly increased after KJ-Pyr-9 application." (PMID 33925297, 2021). "In addition, the correlation between 18F-FDG accumulation and LDHA expression and the possible modulation of 18F-FDG uptake through LDHA-AKT-GLUT1 signaling has been reported in lung adenocarcinoma." (PMID 26509967, 2015). "In lung adenocarcinoma, UPP1 knockdown via shRNA reduced the protein levels of ENO1 and LDHA in H292 and H1975 cells, whereas overexpression of UPP1 restored the suppression of lactate production, glucose uptake and ENO1/LDHA protein levels induced by 2-deoxy-d-glucose in H1299 cells." (PMID 40804482, 2025). "It is hypothesized that LDHA, GPX3 and DOCK4 are new potential targets for lung adenocarcinoma, which can achieve breakthroughs in prognosis prediction, targeted prevention and treatment of lung adenocarcinoma and provide important guidance for anti-tumor." (PMID 38213730, 2024). "The expression of LDHA, CDKN3, and SHC1 were significantly raised in lung adenocarcinoma compared to non-cancer cells, whereas BTK expression was higher in non-cancer than in cancer cells (Figures 8A2, B2, C2, D2)." (PMID 40182622, 2025). "The protein expression of glycolysis‐related enzymes (HK2, LDHA and GLUT1) was confirmed to be decreased in PFD‐treated lung adenocarcinoma cells (A549 and H1299) but not in PFD‐treated lung squamous carcinoma cells by western blotting." (PMID 38140828, 2024). "In a word, our research shows that the expressions of key genes of sphingolipid metabolism, such as LDHA, CDKN3, SHC1 and BTK, are obviously different from those of non-cancerous tissues in lung adenocarcinoma, and can obviously affect the prognosis of LUAD patients." (PMID 40182622, 2025).
cervical cancer (33 papers, 2017 to 2026). A primary or metastatic malignant neoplasm involving the cervix. "A study involving 908 cervical cancer cases demonstrated that serum LDH was universally elevated, with higher LDHA expression typically associated with poorer prognosis." (PMID 41561760, 2025). "In cervical cancer, inhibiting LDHA induces G2/M phase cell cycle arrest and activates the mitochondrial-mediated apoptosis pathway." (PMID 41561760, 2025). "Although most studies indicate that LDHA promotes carcinogenesis by enhancing glycolysis, and its inhibition typically suppresses tumor growth, the opposite trend is observed in cervical cancer." (PMID 41561760, 2025). "In cervical cancer, downregulation of phosphorylated stress-induced phosphoprotein 1 inhibits the progression of cervical cancer by reducing glycolysis and decreasing the level of LDHA." (PMID 36894874, 2023). "Another study also found that a relatively high expression level of LDHA in cervical cancer cells was resistant to RT, which helped cancer cells carry out aerobic glycolysis and promoted radioresistance." (PMID 36313645, 2022). "A study on chemoradiotherapy resistance in advanced cervical cancer showed that the expression of LDHA was up-regulated in chemoradiotherapy resistant group by microarray analysis compared to chemoradiotherapy sensitive group." (PMID 36313645, 2022). "Suppression of lncRNA NEAT1 increased the sensitivity of 5-FU via sponging miR-34a and elevating the expression of LDHA in cervical cancer cells." (PMID 36438563, 2022). "Taken together, the rescue results verified the miR-34a-suppressed glycolysis and 5-Fu resistance were through directly targeting LDHA in cervical cancer cells." (PMID 33645623, 2021). "The results show that FRA1 can inhibit the expression of LDHA and the production of LA in cervical cancer cells, while LPS negatively regulated the inhibitory effect of FRA1 on glycolysis." (PMID 33456361, 2021). "Western blot results demonstrated overexpression of miR-34a significantly down-regulated protein expressions of LDHA in two cervical cancer cells." (PMID 33645623, 2021). "Silencing of LDHA significantly attenuated colony-formation ability and invasive capacity of cervical cancer cells." (PMID 30356100, 2018). "Levels of HPV16 E7, nuclear LDHA expression, and H3K79 trimethylation were significantly positively correlated with each other, strongly supporting the crucial role of nuclear LDHA in HPV-positive cervical cancer." (PMID 30356100, 2018). "Here the authors propose a model in which the infection of epithelial cells with high risk HPV results in a burst of reactive oxygen species, translocation of LDHA to the nucleus and activation of a gene profile that supports the growth of cervical cancer." (PMID 30356100, 2018). "The key glycolysis enzyme LDHA was identified to be a potential key regulator in HPV-induced cervical cancer development." (PMID 30356100, 2018). "Accordingly, whether LDHA inhibition strategies are applicable for targeted therapy in cervical cancer warrants further investigation." (PMID 41561760, 2025). "Targeting histone lactylation through inhibitors of LDHA or MCTs may reduce immunosuppression and enhance the effectiveness of ICIs in cervical cancer." (PMID 41029427, 2025). "Nevertheless, LDHA inhibition may promote tumor growth in cervical cancer models, suggesting limited applicability across gynecological tumors." (PMID 41561760, 2025). "Previous studies have identified potential marker genes (CSF1R, ERAP1, LDHA, etc.,) that may affect response rate by reshaping the cervical cancer microenvironment." (PMID 38206304, 2024). "In this study, LDHA showed multiple correlations with immune invasion of cervical cancer." (PMID 36894874, 2023). "It was reported inhibition of LDHA reduced the proliferation and invasion of cervical cancer cells." (PMID 36313645, 2022).
cervical cancer (continued). "In addition, LDHA, CCL4, and PKM were reported to be associated with the development, proliferation, or progression of cervical cancer cells." (PMID 36284631, 2022). "In addition, glycolysis inhibition by either glycolysis inhibitor or LDHA knockdown led to increased 5-Fu sensitivity of cervical cancer cells." (PMID 33645623, 2021). "Finally, we demonstrated inhibition of NEAT1 significantly sensitized cervical cancer cells to 5-Fu through the miR-34a/LDHA pathway." (PMID 33645623, 2021). "To identify whether LDHA was the direct target of miR-34a in cervical cancer cells, we constructed luciferase plasmids pGL3-LDHA-WT or pGL3- LDHA-Mut, which contain wildtype or miR-34a binding site mutant 3′UTR of LDHA." (PMID 33645623, 2021). "Our findings suggest that targeting the NEAT1-mediated miR-34a/LDHA-glycolysis axis might be regarded as a promising therapeutic strategy against chemoresistant cervical cancer." (PMID 33645623, 2021). "However, some of them have been found to associate with other cancers via diversified mechanisms, for example, nuclear LDHA promoted HPV-induced cervical cancer development using a mechanism of H3K79 hypermethylation." (PMID 33134164, 2020). "As such, blocking LDHA nuclear translocation may offer more opportunities to cervical cancer prevention and ROS-based cancer therapies." (PMID 30356100, 2018). "It should be noted that besides the classical enzymatic function in the cytoplasm, LDHA translocates into the nucleus in response to excessive ROS, and nuclear LDHA gains a non-canonical enzymatic activity to produce antioxidant metabolites in cervical cancer cells." (PMID 40710803, 2025). "Importantly, knocking down NEAT1 successfully down-regulated LDHA expressions and glycolysis rate of cervical cancer cells by up-regulating miR-34a, a process could be further rescued by miR-34a inhibition." (PMID 33645623, 2021). "Genes such as LDHA, ACACA, and SLC16A3 are upregulated in cervical cancer, contributing to lactate-mediated epigenetic changes that suppress DC and T-cell activity." (PMID 41029427, 2025). "In summary, GF2 increased the cytotoxicity and the sub-G1 phase along with the suppression of pro-PARP, pro-cas3, Wnt, β-catenin, c-Myc, HK2, LDHA, and PKM2 in cervical cancer cells." (PMID 39273365, 2024). "High expression of GLUT1, LDHA, and MCT4 proteins has been observed in biopsies from patients with invasive cervical cancer." (PMID 36678382, 2022). "HPV16 E7 level is significantly positively correlated with nuclear LDHA and H3K79 tri-methylation in cervical cancer." (PMID 30356100, 2018). "To investigate the potential role of LDHA in HPV-induced cervical cancer, we collected HPV-negative and HPV-positive cervical cancer specimens from 66 patients." (PMID 30356100, 2018). "Glycolytic activation in cervical cancer is partially achieved by the HPV oncoprotein E6, which downregulates miR-34a, resulting in the upregulation of the miR-34a target and glycolytic enzyme lactate dehydrogenase A (LDHA)." (PMID 37298494, 2023). "These genes were uploaded to the GEPIA database, which showed that in cervical cancer and paracancerous tissues, the expression levels of seven genes, CD47, FKBP4, IRF-1, LDHA, PDIA3, TFRC, and SLC16A1, were significantly higher in cancer tissues (p < 0.05) than in healthy tissues." (PMID 36894874, 2023). "Interestingly, an aggregation of intracellular ROS can disassemble the LDHA tetramer, concurrently augmenting nuclear LDHA concentration in Human papilloma virus (HPV) 16 E7 oncoprotein‐positive cervical cancer cells." (PMID 38034101, 2023). "The process of aerobic glycolysis in cervical cancer cells is mediated by key enzymes such as glucose transporter 1 (GLUT1), LDHA, hexokinase 2 (HK2) and aldolase A (ALDOA), which enhance glucose uptake and lactate production, and promote the progression of cervical cancer." (PMID 36313645, 2022).